MMP9 (matrix metallopeptidase 9)
Diseases named in the same sentence as MMP9 in open-access papers (continued):
Sharing a sentence is not in itself a finding about the gene and the disease.
gastric cancer (continued). "In the present study, Grhl2 reduces MMP-2, MMP-7 and MMP-9 expression, which is partly explained by the mechanism by which Grhl2 inhibits gastric cancer cell invasion and migration, but this is obviously not enough." (PMID 28067907, 2017). "In gastric cancer cells, BMP-2 enhanced the phosphorylation/degradation of IκBα and the nuclear translocation/activation of NF-κB, as well as phosphorylation of AKT and ERK, leading to MMP-9 expression." (PMID 28350359, 2017). "The patients of gastric cancer were stratified either minimal-invasive group (MMP-9 low-expression; n = 94) or highly invasive group (MMP-9 over-expression; n = 98) according to the expression of MMP-9 potein." (PMID 28404958, 2017). "PEITC suppresses metastasis of human gastric cancer cells by inhibiting MMP-2 and MMP-9." (PMID 28969043, 2017). "SLPI promoted migration, invasion and metastasis of gastric cancer cells by increasing expression of MMP-2 and MMP-9 genes, and the latter could have been targeted by transcriptional factor FoxM1." (PMID 29312532, 2017). "Additionally, under pathological conditions including gastrointestinal inflammation and gastric cancer, MMP-9 can be derived from stromal cells, such as inflammatory cells and fibroblasts, and enhanced level of MMP-9 has been described." (PMID 29228747, 2017). "In addition, these Chinese researchers found that the genotype of MMP-9 is correlated with TNM classification and lymph node metastasis and plays an important role in the progression and metastasis of gastric cancer." (PMID 29228747, 2017). "Our results suggest that chrysin may exert at least part of its anticancer effect by controlling MMP-9 expression through suppression of AP-1 activity via a block of the JNK1/2 and ERK1/2 signaling pathways in gastric cancer AGS cells." (PMID 25875631, 2015). "Effects of luteolin administration on the expressions of cMet, p-cMet, Akt, p-Akt, ERK, p-ERK, MMP9 and Ki-67 in PDTX models of gastric cancer cMet-overexpression in gastric cancer is accompanied by abnormal activation of cMet signaling that contributes to tumor survival, growth and metastasis." (PMID 25638174, 2015). "MMP2, MMP7 and MMP9 have been most extensively investigated in gastric cancer, but never previously in a direct comparison and in association with mTOR expression." (PMID 26652716, 2015). "In our study, AP-1 decoy oligodeoxynucleotides, AP-1 inhibitor curcumin, c-Jun and c-Fos siRNA interfered with PMA-induced MMP-9 expression, which provided direct evidence that AP-1 is critically required to increase MMP-9 transcription in gastric cancer cells." (PMID 25875631, 2015). "MMP-9 mRNA and serum expression were upregulated in gastric carcinoma, however, the present study did not observe a correlation between MMP-9 expression levels in the gastric carcinoma tissues and those in the preoperative serum." (PMID 25621068, 2015). "Moreover, upregulation of FENDRR has the effect of suppressing gastric cancer cell migration and invasion in vitro by targeting FN1 and MMP2/MMP9." (PMID 25167886, 2014). "Since previous studies reveal the critical roles of MMP-7, MMP-9 and MMP-14 in the invasion and metastasis of gastric cancer, we hypothesized that MJ might influence the expression of these genes." (PMID 23394613, 2013). "Western blot indicated that administration of sub-cytotoxic (0.1 and 0.2 mM) MJ resulted in a decrease in the expression of MMP-14, but not of MMP-7 or MMP-9, in cultured gastric cancer SGC-7901 and MKN-45 cells." (PMID 23394613, 2013). "Real-time quantitative RT-PCR revealed the decreased transcript levels of MMP-14, but not of MMP-7 or MMP-9, in gastric cancer cells treated with sub-cytotoxic MJ." (PMID 23394613, 2013). "To figure out the possible mechanisms of how IGFBP3 regulate the invasiveness of gastric cancer cells, we examined the mRNA levels of MMP2/MMP7/MMP9/MMP14, TIMP1/TIMP2, uPA and its receptor uPAR, all of which are invasion-related factors, especially in gastric cancer." (PMID 24386080, 2013).
gastric cancer (continued). "In this study, we found that sub-cytotoxic MJ selectively down-regulated the expression of MMP-14, but not of MMP-7 and MMP-9, in gastric cancer cells." (PMID 23394613, 2013). "Correlation analysis between CXCR1/2 and pAKT (P=0.032), pERK (P<0.001), Cyclin D1 (P=0.049), EGFR (P=0.013), Bcl-2 (P=0.003), microvessel density (P=0.001), MMP-9 (P=0.013) and MMP-2 (P=0.027) expression using the Spearman test showed significant correlation in gastric carcinoma." (PMID 23420470, 2013). "For example, Shh signaling could promote the metastasis of gastric cancer cells through activation of the PI3K/Akt pathway, which may lead to epithelial mesenchymal transition and MMP-9 activation." (PMID 22615870, 2012). "Therefore, we examined the effect of coronin 3 knockdown or up-regulation on the expression of MMP-9, cathepsin K (based on the results of the PCR array), MMP-2, TIMP-1 and TIMP-2 in gastric cancer after infection." (PMID 22974233, 2012). "Moreover, knockdown of CTGF expression also markedly reduced the migration and invasion of gastric cancer cells and decreased the expression of matrix metalloproteinase (MMP)-2 and MMP-9." (PMID 21955589, 2011). "CD147 expression was gradually increased from normal mucosa to carcinomas through hyperplastic or metaplastic mucosa of the stomach, and its expression was positively correlated with tumor size, depth of invasion, lymphatic invasion and expression of ki-67, MMP-2, MMP-9 and VEGF in gastric cancer." (PMID 20525232, 2010). "As negative regulators in Wnt signaling, Secreted Frizzled-Related Proteins (SFRPs) are downregulated in a series of human cancers; and specifically, some matrix metalloproteinases (MMPs), including MMP-2, MMP-7, MMP-9 and MT1-MMP, are frequently overexpressed in gastric cancer." (PMID 19586554, 2009). "The value of MMP-2 as an independent prognostic marker for gastric carcinomas is underscored by our observation that MMP-9, MMP-7, MMP-8, TIMP-1 and TIMP-2 have no prognostic relevance." (PMID 16538217, 2006). "Finally, it can be mentioned that, with the help of continuous bioinformatics analyses, BGN, LOX, MMP-9, SERPINE1, and TGFB1 proteins enhance the progression of gastric cancer; they play a significant role in the organization and communication of cells in the extracellular matrix." (PMID 34054953, 2021). "Due to the great potential of these three markers (HER-2, MMP-2, and MMP-9) in the prognosis and treatment of advanced stages of gastric cancer, and the absence of investigations directly comparing MMP-2 andMMP-9 with HER-2 expression, we decided to evaluate this subject." (PMID 33773545, 2021). "It was also reported that MMP2 in renal carcinoma cells, MMP9 and MMP14 in osteosarcoma cells could increase soluble MICA and MMP9 specific inhibitor could increase MICA/B and ULBP2 in some kinds of gastric cancer cells." (PMID 34253166, 2021). "The clinical indicators of serum matrix metalloproteinase 9 (MMP-9), serum interleukin-2 receptor (SIL-2R), and immune cell level were detected in the two groups before and after treatment to analyze the therapeutic effect of different treatment methods on patients with advanced gastric carcinoma." (PMID 34422049, 2021). "Concerning different anti-MMP-9 strategies, humanized anti-MMP-9 monoclonal antibodies (ANDECALIXIMAB) have been explored in gastric cancer patients, and found to be safe (with no indication of musculoskeletal side effects) and moderately effective when combined with classical cytotoxic drugs." (PMID 32630531, 2020). "Interestingly, MMP9 mainly promotes tumor invasion and metastasis, while TIMP-1 inhibits the functions of MMP9 in gastric cancer, which suggests that the imbalance between MMP9 and TIMP-1 expression may occur in tumor progression." (PMID 31816819, 2019). "Therefore, 28-hydroxy-3-oxoolean-12-en-29-oic acid may inhibit the invasion and migration of gastric cancer cells by downregulating the protein expression of MMP-2 and MMP-9." (PMID 31569766, 2019).
gastric cancer (continued). "For instance, long intergenic non‐coding RNA 01296 (LINC01296) acts as oncogenic lncRNA in GC carcinogenesis and aggravates gastric cancer cells progress via LINC01296/miR‐122/MMP‐9 regulatory pathway." (PMID 30006956, 2018). "Therefore, we tested the changes of MMP-2, MMP-7 and MMP-9 after Grhl2 overexpression in both SGC7901 and MKN45, so as to preliminarily clear the possible mechanisms by which Grhl2 inhibits invasion and migration of gastric cancer." (PMID 28067907, 2017). "Although Snail was reported to be a downstream target of AEG‐1 or eIF4E in other types of cancers, it was not the key molecule involved in the AEG‐1/eIF4E pathway in gastric cancer metastasis in this study, as it did not changed in the same pattern as MMP‐9 and Twist did." (PMID 28661037, 2017). "The current study identified that the inhibitory effect of KAI1 expression on the cell migration and invasion of gastric cancer was not mediated by HIF-1α, MMP-2 and MMP-9, but may be associated with the reduction in uPA and bFGF expression." (PMID 26622792, 2015). "However, the inhibitory effects of chrysin on MMP-9, as well as the mechanism, have not been well studied, especially in gastric cancer cells." (PMID 25875631, 2015). "However, the correlation between MMP-9 mRNA levels in gastric carcinoma tissues and the preoperative serum MMP-9 levels was not identified to be statistically significant (r=0.13; P=0.394)." (PMID 25621068, 2015). "Furthermore, the claudin-4-expressing gastric cancer cells were found to increase MMP-2 and MMP-9 expression, indicating that claudin-mediated increased cell invasion may be the result of MMP protein activation." (PMID 25120725, 2014). "This study was to determine the roles of MMP-9, MMP-2, type IV collagen, infiltrating macrophages and tumor microvessels in gastric cancer (GC) invasion and their clinico-pathological significance." (PMID 20950454, 2010). "Moreover, MMP-9 antigen levels in normal as well as tumour tissue of gastric cancer patients with the MMP-9−1562C>T genotype were not enhanced, as was recently also found in plasma of healthy subjects." (PMID 16940985, 2006). "In the same way, we found that COL4A1 silence downregulated the expressions of Ki67, PCNA, MMP2, MMP9, N-cadherin and Vimentin but promoted E-cadherin expression in MKN-45 cells, revealing that COL4A1 silence could help to suppress the proliferation, metastasis and EMT in gastric cancer." (PMID 35297303, 2022). "However, the role of sulforaphane in MMP-9 expression in gastric cancer is not yet defined." (PMID 35563563, 2022). "However, the effects of chrysin on MMP-9 expression in gastric cancer have not been well studied." (PMID 25875631, 2015). "Similar results obtained in HCC and CCA patients were found in other cancers such as patients with gastric cancer, colorectal cancer, and pancreatic cancer: a significant negative correlation was found between RECK and MMP-2/MMP-9 expression." (PMID 38139236, 2023). "For instance, human placenta or ESCC tissues and culture supernatants of MKN1 (gastric carcinoma) and TE-7, -8, -9, and -10 (ESCC) cells did not contain active form MMP9, although they all express proMMP9." (PMID 37296952, 2023). "In gastric cancer (GC), SIRT1 silencing or inhibiting its activity by EX527 enhances expression of FOXO1, pro-apoptotic BAX, and E-cadherin, whereas the expression of Ki67, Cyclin D1, anti-apoptotic Bcl-2, Vimentin, MMP-2 and MMP-9 are downregulated, suggesting SIRT1 involvement in GC progression." (PMID 34769241, 2021). "We proved that our tested combination of OM-86II with the anti-MUC1 antibody reduced only MMP-9, but not MMP-2 concentration in AGS gastric cancer cells." (PMID 34770912, 2021). "Serum levels of MMP-9, but not MMP-2, are significantly higher in colorectal and gastric cancer compared to controls." (PMID 19924065, 2009).
gastric cancer (continued). "Although gelatinase B/MMP-9 is not required for normal skin lymphangiogenesis, tumour induced lymphangiogenesis has been reported to involve a sonic hedgehog/PI3K/Akt/gelatinase B/MMP-9 pathway, leading to lymph node metastases in gastric cancer." (PMID 24473089, 2014). "In addition to ERBB2 and PERLD1, the TRAC analysis also identified five novel genes, CYP3A4, ENAH, MMP9, PTPRA, and OSMR, which have not been reported as gained and overexpressed in gastric cancer before." (PMID 20187983, 2010).
prostate carcinoma (384 papers, 2006 to 2026). A carcinoma that arises from epithelial cells of the prostate gland. "Curcumin treatment caused a noteworthy reduction in MMP-2 and MMP-9 expression, in conjunction with reduced cellular invasion in vitro in prostate cancer cells (DU-145)." (PMID 34456716, 2021). "Cancer-cell proliferation is significantly suppressed in tumors from MMP9-deficient mice, and it has been demonstrated that MMP9 regulates the insulin-like growth factor-triggered to induce cell proliferation in prostate cancer." (PMID 33659208, 2020). "Activation of MMP-9 led to the cell migration, and the upregulated MMP-9 are associated with invasion, metastasis and poor prognosis in different types of cancers such as colon, ovarian and prostate cancer." (PMID 30013454, 2018). "Specifically, increased expression of MMP-2 and MMP-9 has been shown to be associated with prostate cancer progression and metastasis." (PMID 27340776, 2016). "Transcriptome profile showed that RUNX2 was associated with the malignant behavior of prostate cancer, including invasion and bone spread by up-regulating MMP9, SNAI2 and Smad3." (PMID 27007162, 2016). "Compared with benign prostate tissue, higher NF-κB levels are detected in low- and high- grade prostate cancer specimens and are associated with the expression of NF-κB–regulated gene products including Bcl2, cyclinD1, MMP-9, and VEGF." (PMID 26379052, 2015). "One study has reported that MMP9 overexpression in prostate cancer is associated with ERK overexpression." (PMID 24348851, 2014). "In particular, MMP-2 and MMP-9 have been implicated in the invasive potential of PC-3 prostate cancer cells." (PMID 25248616, 2014). "In particular, MMP-2 and MMP-9 have been suggested to be associated with prostate cancer metastasis, as high levels of these proteins were measured in plasma and urine in patients with metastatic disease." (PMID 19956729, 2009). "Both MMP2 and MMP-9, in particular, have been found to be associated with prostate cancer metastasis." (PMID 19956729, 2009). "FGF2 has been described in prostate cancer and implicated in cancer invasion and metastasis, probably through upregulation of MMP9, which was also upregulated in our study." (PMID 18211683, 2008). "In prostate cancer fibroblast and tumor microenvironment models, AR activation has been linked to upregulation of MMP-9/VEGF signaling via PIP5K1α/AKT crosstalk, implicating a molecular axis by which androgen signaling promotes proteolysis and vascular remodeling in tumor stroma." (PMID 41304763, 2025). "OPN expression and MMP-9 activity are linked to the progression and metastasis of prostate cancer." (PMID 31331331, 2019). "MMP9 plays a significant role in prostate cancer progression and is secreted in association with the motor protein myosin IC, whose nucleocytoplasmic distribution in prostate cancer cells is regulated by calcium." (PMID 29921791, 2018). "Additionally, we also investigated the possibility that WNT5A signaling caused a reduced secretion of MMP9 in prostate cancer cells." (PMID 28886116, 2017). "Moreover, knockdown of Notch1 inhibited invasion of human prostate cancer cells in association with inhibition of matrix metalloproteinase-9 (MMP-9) and urokinase plasminogen activator." (PMID 22970326, 2012). "Expression of MMP-2 and MMP-9 are associated with prostate cancer progression." (PMID 21629786, 2011). "In prostate cancer BRCA2 has been associated to promotion of invasion through upregulation of MMP9." (PMID 20805891, 2010). "MMP-2 and MMP-9 are associated with metastasis of prostate cancer cells to bone." (PMID 17343740, 2007). "OPN expression and MMP-9 activity are linked to prostate cancer cell progression and metastasis." (PMID 17343740, 2007). "For example, MMP-9 analysis in prostate cancer showed elevated protein levels in cancer tissue, but without a corresponding mRNA-protein correlation." (PMID 39996799, 2025).